CCR4 (C-C motif chemokine receptor 4)
Diseases named in the same sentence as CCR4 in open-access papers (continued):
Sharing a sentence is not in itself a finding about the gene and the disease.
tumor (continued). "Chemokines (CXCL12, CXCL8, CXCL5) and chemokine receptors (CXCR1/2, CCR4, CCR8) are well-known to deeply participate in the tumor development and progression in various cancers, including LUAD." (PMID 36419650, 2022). "The receptor CCR4 has low expression on CD8+ T cells, but its ligands CCL22 and CCL17 recruit pro-tumoural TH2 and regulatory T cells to the tumour to support tumour growth." (PMID 35205725, 2022). "Tumor cells and cells in the tumor microenvironment secrete high amounts of CCL22, a ligand for CCR4, in various cancers." (PMID 33679808, 2021). "CCL2 was a common chemokine that recruits monocytes, memory T cells, and dendritic cells during tumor progression through the CCL/CCR2 and CCL2/CCR4 signaling." (PMID 34580284, 2021). "Tregs recruitment occurs through the binding of CCR4 on Tregs surface and CCL22 secreted by GBM tumour cells and CD163+ TAMs, under the induction of tumour-derived CCL20 and osteoprotegerin." (PMID 33804731, 2021). "PDAC (and other tumours) secrete high amounts of cytokines (CCL17; CCL22) which bind to the CC chemokine receptor 4 (CCR4) primarily expressed on Tregs." (PMID 34439389, 2021). "Molecular targets for MS/SS are currently CD30, CCR4, CD25, CD52, and histone deacetylases, most of which are surface molecules specifically expressed on tumor cells." (PMID 34681738, 2021). "The first report on CAR T cells co-expressing CCR was from Di Stasi's team where they revealed that CCR4-modified CD30-CAR T cells improved homing and anti-tumor activity in a Hodgkin tumor model." (PMID 33777013, 2021). "Th17 cells express CCR4 and CCR6, which are considered to be involved in their recruitment into the tumor microenvironment." (PMID 34885241, 2021). "In a phase I study, the safety and efficacy of combined mogamulizumab (anti-CCR4 antibody) and nivolumab are evaluated for patients with HCC, with four (27%) tumor responses among 15 patients." (PMID 33854960, 2021). "When incubated with mesothelin-positive tumor cells, Msln-CCR2b-CAR and Msln-CCR4-CAR T cell specifically exerted potent cytotoxicity and produced high levels of proinflammatory cytokines, including IL-2, IFN-γ, and TNF-α." (PMID 33777013, 2021). "A CCR4 antagonist, FLX475, has shown to effectively inhibit Treg migration into the TME and deplete effector Tregs in many tumor models." (PMID 34806028, 2021). "Tumor cells in both MF and SS are typically CD4+CCR4+ memory T cells and some MF cases develop into SS." (PMID 34681738, 2021). "It has been previously reported that blocking CCR4, the CCL17 receptor, inhibits tumor growth and prolongs survival." (PMID 33664865, 2021). "The treatment with an anti-CCR4 antibody induced robust ADCC leading to reduced tumor mass, accompanied by decreased Treg frequencies in the tumor." (PMID 33679808, 2021). "MF and SS share common features, such as epidermotropism of tumor cells and CD4, CD45RO, and CCR4 expression in tumor cells." (PMID 34360654, 2021). "As CCR4− effector CD8 T cells are rarely present at the tumor site, the strategy of generating CAR T cells that co‐express CCR4 resulted in higher in vivo migratory and antilymphoma activities." (PMID 32620049, 2020). "Protein-protein interaction (PPI) and Cox regression analysis were performed on the differentially expressed genes (DEGs) to identify four key tumor microenvironment (TME) -related genes (CCR2, CCR4, P2RY12, and P2RY13)." (PMID 33318300, 2020). "In this context, CCR4 is highly expressed in human RCC biopsies and, in a mouse model of RCC, anti-CCR4 mAb was shown to exhibit anti-tumor activity." (PMID 32013092, 2020). "The CAR-CD30 T cells expressing CCR4 significantly enhanced the CAR T migration to tumor sites and achieved satisfactory tumor control in a Hodgkin tumor model." (PMID 33381115, 2020).
tumor (continued). "The results of correlation analysis between the expression of significant genes and tumor-infiltrating immune cells showed that the expression of CCL5, CCL8, CCR4, and CCR5 were all correlated with the level of tumor immune cell infiltration." (PMID 33181717, 2020). "The rationale of overexpressing CCR4 is to allow for CAR-T migration and homing to the tumor microenvironment." (PMID 33050054, 2020). "CCL2 produced by murine GBM cells recruits CCR4+Tregs and CCR2+Ly-6C+ mMDSCs while MIF produced by tumor stem cells activates MDSCs, resulting in an immunosuppressive tumor microenvironment." (PMID 32707672, 2020). "Human malignant glioma lines and fresh tumor tissue express elevated CCL2, and nTreg obtained from patient samples express elevated CCR4." (PMID 31681327, 2019). "Work by Peng's group showed that tumor-derived fibroblasts secreted MCP-1 (known as CCL2), the ligand for CCR2 or CCR4, and RANTES (known as CCL5), the ligand for CCR1, CCR3, or CCR5." (PMID 30800130, 2019). "As a prognostic factor in BrCa, tumor derived CCL22 has also been shown to activate and recruit CCR4 expressing Tregs56,57." (PMID 30850664, 2019). "The chemokine receptors CCR1, CXCR3, CCR4 and CCR5 were found to be heterogeneously expressed in ALCL tumor cells." (PMID 31581676, 2019). "CCR4 expression is positively correlated with HER2 expression, tumor recurrence, and lymph node, lung, and bone metastasis of breast cancer." (PMID 31672162, 2019). "CCR4 has been validated as a CAR-T target as Perera and colleagues have demonstrated the ability of an anti-CCR4-CAR to lyse multiple T-cell lines in vitro and clear T-ALL tumor in a xenograft mouse model." (PMID 31058076, 2019). "It is also possible that depletion of CCR4-expressing T cells leaves other tumor-infiltrating Tregs unaffected, such as the CCR8-expressing Tregs that have been noted in multiple tumor types." (PMID 31801624, 2019). "(c) Expression of CCR2, CCR4, CCR5, CCR7, CXCR1, CXCR2 and CXCR7 on tumor-infiltrating mast cells by gating on CD45+CD117+FcεRI+ cells." (PMID 30808413, 2019). "CCL22 and CCL28, expressed in many human tumors, are mediators for the recruitment of CCR4+/CCR10+ Treg cells, involved in the suppression of both spontaneous and therapy-induced local tumor immunity." (PMID 30319638, 2018). "Regulatory T cells (Treg), known to suppress antitumor immunity, express CCR4 and CCR10, by which they are recruited into the tumor microenvironment." (PMID 30591657, 2018). "The dominant pathway for Treg recruitment is through tumor- or TAM-derived CCL22 that binds CCR4 on Tregs, providing rationale for CCR4 antagonists." (PMID 30355585, 2018). "However, it still remains unclear how mutations on CNOT3 or other CCR4-NOT subunits can contribute to tumor development." (PMID 30144809, 2018). "Since, induced FoxP3 are downregulated for CCR7 and CD62L as well as upregulated for memory or effector-type trafficking receptors such as CCR4, CCR5, CCR8, CCR10, and/or CXCR4, they can migrate into the tumor via the tumor-draining lymph nodes." (PMID 29450136, 2017). "In this study, we initially demonstrated that CCR4 is overexpressed in HCC specimens, and its elevation in HCC tissues positively correlates with tumor capsule breakthrough and vascular invasion." (PMID 28959024, 2017). "In the present study, expression level of MMP13 was found to be decreased under condition of CCR4 knockdown, while overexpression of CCR4 increased the level of MMP13 in tumor cells." (PMID 27356745, 2016). "After administration of a CCR4 antagonist, we observed inhibition of SCC-VII tumor growth at day 33 (P < 0.01 for each) and prolongation of the overall survival time (P < 0.05 for each) in the CCR4 antagonist-treated group compared to the control groups." (PMID 27177223, 2016).
tumor (continued). "To further explore the molecular mechanisms that CCR4 involved in CRC cells invasion, we analyzed metastasis-related genes for SW1116/CCR4 cells and SW1116/Vector cells using a Tumor Metastasis PCR Array." (PMID 27356745, 2016). "The chemoattractant properties of CCR4/CCL22 and CCR4/CCL17 for Treg cells were assessed using the Boyden chamber technique, to elucidate the potential mechanisms of Treg recruitment in tumor microenvironment." (PMID 26020249, 2015). "In tumor microenvironment, Th1 cells express CCR5 and CXCR1, Th2 cells express CCR4 and CCR8, whereas regulatory T cells mainly express CCR4." (PMID 25768730, 2015). "The initially secreted chemokines at the tumor site play a key role defining the composition of the tissue stroma and recruiting tumor infiltrating leukocytes bearing specific chemokine receptors (CXCR1, CXCR2, CCR2, CCR4, or CCR5, among others)." (PMID 25688243, 2015). "Circulating Treg cells were recruited to tumor tissue via CCR4/CCL22 signalling, whereas tumor-synthesised TGF-β contributed to induction of peripheral Treg cells." (PMID 26020249, 2015). "Mogamulizumab (KW–0761) is a mAb that targets CCR4(+) tumor cells by ADCC and downregulates Treg trafficking to the tumor microenvironment." (PMID 25355407, 2014). "As a mechanism of Treg recruitment to tumors, it has been proposed that the tumor cells and tumor infiltrating macrophages produce the chemokine CCL22, which attracts and recruits CD25+ CD4+ Tregs expressing CCR4." (PMID 25080123, 2014). "Therefore, the antibodies targeting the chemokine receptor CCR4 may possess dual or multiple mode of action in some cancer indications, such as targeting the CCR4+ tumor cells and modulation of immunosuppressive tumor microenvironment including infiltrating Treg cells." (PMID 25080123, 2014). "Several studies indicate that the tumor-expressed chemokines CCL22 and CCL17, which are ligands for CCR4, play a role in the recruitment and enrichment of Tregs." (PMID 23874342, 2013). "CCL2 produced by cancer cells recruits MDSCs into tumor and CCL22 produced by M2 macrophages recruits CCR4+ Tregs and Th2 cells into tumor and sentinel lymph nodes." (PMID 23755373, 2013). "The frequencies of cells expressing α4β7 and the Th1 associated chemokine receptor CXCR3 were significantly decreased among CD4+ T cells in the tumor, while frequencies of CD4+CCR4+ lymphocytes were significantly increased." (PMID 22319577, 2012). "Although most of the recently activated Tregs were capable of migrating to the tumor microenvironment (as determined by CCR4+ expression), CD38+ effector T cells were mostly CCR4−." (PMID 24213326, 2012). "In contrast, CCR4, a chemokine receptor associated with Th2 and Treg responses, was reciprocally expressed, i.e. there was a higher frequency of CCR4+ cells in CD4+ conventional T cells and Treg in the tumor than in the unaffected mucosa." (PMID 22319577, 2012). "Thus, targeted therapy against CCR4 may be an attractive treatment option for these malignancies, not only to directly kill the CCR4+ tumor cells, but also to overcome the suppressive effect of CCR4+ Tregs on the host anti-tumor immune response." (PMID 22973452, 2012). "CCR4+ Mac-1 tumor cells grow well in SCID-BEIGE mice and therefore we established a SCID-BEIGE/Mac-1 xenograft tumor model to evaluate the efficacy of AAV8-h1567 therapeutic minibody gene transfer." (PMID 22973452, 2012). "A recent study identified circulating and tumor infiltrating CD28+ CD8+ Tregs with a CD25+, FOXP3+, CTLA-4+, GITR+, CCR4+, TGF-β+ and CD127low/neg phenotype." (PMID 24212779, 2011). "Co-expression of CCR4 improved the homing ability of anti-CD30 CAR-T cells to Hodgkin tumor sites by enhancing their migration toward CCR4 ligands CCL17 and CCL22, which are highly expressed in the tumor microenvironment." (PMID 41181132, 2025).
tumor (continued). "Experiments in mice suggested that the blockade of the homing receptor (CXCR4) and chemokine receptor (CCR4/CCR8) may inhibit Treg infiltration and tumor homing." (PMID 40427000, 2025). "As discussed with CCR4-targeting therapies, denileukin diftitox also depletes CD25+ regulatory T cells, offering a dual rationale though modulation of the TME and augmentation of tumor immune responses." (PMID 41295262, 2025). "Moreover, Mogamulizumab, an anti-CCR4 monoclonal antibody, effectively eliminates Tregs through ADCC in adult T-cell leukemia-lymphoma patients, significantly increasing tumor-specific CD8+ T cells and promoting secretion of IFN-γ and TNF-α." (PMID 40607438, 2025). "In a clinical trial involving patients with CCR4-negative solid tumours, tumour regression in response to mogamulizumab was rarely observed." (PMID 41291326, 2025). "Additionally, pro-inflammatory factors upregulate chemokine receptors such as CCR1, CCR4, and CXCR7, enabling tumor cells to metastasize to specific organs." (PMID 39981173, 2025). "This expansion is orchestrated by the tumor microenvironment, where immunosuppressive cytokines such as TGF-β and IL-10 induce naïve T cell conversion into Tregs, and chemokines like CCL22 mediate recruitment via CCR4 signaling." (PMID 41181112, 2025). "Treg recruitment into the TME is accomplished via CCR4/CCL22 or CCR4/CCL17 pathways after interactions between CCR4+ Tregs and CCL22/CCL17 secreted by TAMs and tumor cells; as such, CCR4+ Tregs abundantly infiltrate the TME and are considered the most immunosuppressive subset of Tregs." (PMID 40649958, 2025). "Moreover, they express chemokine receptors, such as CCR4, CCR5 and CCR10, which facilitate chemotactic migration of Tregs into the tumor microenvironment." (PMID 38500876, 2024). "Given the vital role of CCL22 and its receptor CCR4 on Tregs recruitment and tumor progression, we hypothesized that CCL22‐CCR4 axis was involved in SOX12‐induced Tregs enrichment." (PMID 39072947, 2024). "In a subset of individuals with CCR4+ ATLL, the tumour cells may act as regulatory T-regs cells, promoting tumour immune escape." (PMID 38804300, 2024). "Tumor tissues with high CCL17-T levels generally had high CCR4-I expression, suggesting that HCC cells might secrete CCL17 to recruit CCR4 + stroma cells (p < 0.001)." (PMID 38914802, 2024). "Here, we selected CCR4 and CCR7, which showed the highest ratio of draining to contralateral lymph node enrichment and a particularly high specific enrichment into draining lymph node over the tumor." (PMID 37301772, 2023). "The CCR4 interaction with CCL12 activates intracellular signaling that activates various pathways such as NF-Kb, RAS-MAPK, JAK-STAT, P13K-AKT-mTOR, and PLC-Ca2+, which can regulate angiogenesis, tumor cell proliferation, and apoptosis inhibition." (PMID 37259456, 2023). "CCR4 is predominantly expressed by effector Treg cells and not by naive Treg cells and Th2 cells, which do not contribute significantly to tumor-immunity regulation in humans." (PMID 36839882, 2023). "TAMs‐released CCL22 activates intratumoral CCR4/FAK/AKT axis, which induces the phosphorylation of Gli1 Ser112/Thr115/Ser116 sites, and stimulates Gli1 activity to induce the stemness and metastasis of tumor cells." (PMID 37846367, 2023). "The observed increase in the abundance of CCR1, CCR4 and/or CCR5+CD8+ T cells may reflect an RT-induced T-cell response directed against NPC tissue, after which these T cells efflux from the tumor into the blood of responding patients." (PMID 36980772, 2023). "The activation of mitogen-activated protein kinase (MAPK) activates the c-myc transcription factor, which regulates CCR4 overexpression, therefore leading to positive and negative feedback, promoting tumor growth and cell proliferation." (PMID 37259456, 2023).
tumor (continued). "We therefore list some possible target molecules (CD25, CD103, CD73, CCR4, CTLA-4, GITR, and Gr1) for NIR-PIT that induce knockdown of immune suppressor cells, especially Tregs, in the tumor microenvironment in order to activate anti-tumor responses." (PMID 36839882, 2023). "Notably, Tregs are recruited to tumour tissues via chemokines, such as CCL22 binding to CCR4 expressed by Tregs, to induce an immunosuppressive tumour microenvironment." (PMID 37275413, 2023). "Injection of the pharmacological CCR4 inhibitor alone without tumor cell inoculation was well tolerated and was not fatal in any animal (n = 20) investigated over 90 days." (PMID 37371612, 2023). "Given the role of CCR4 and CCR3 in recruiting T cells and other immune cells to the tumor, the enhanced expression of these chemokine receptors on transferred Foxp3UP CD8 T cells may also explain their increased numbers in the tumors." (PMID 36045586, 2023). "Modifying the tumor microenvironment, possibly through CCL22 or CCR4 inhibition, may deter Treg recruitment." (PMID 38115302, 2023). "Tumor growth and survival were monitored under prophylactic and therapeutic application of a CCR4 antagonist (AF-399/420/18025) in wildtype (CCR4wt) and CCR4-knockout (CCR4−/−) mice." (PMID 37371612, 2023). "Lastly, because CCR4 and CCR6 both conferred increased therapeutic efficacies, we tested whether co-transduction of these two chemokine receptors improves anti-tumor efficacy." (PMID 37301772, 2023). "For more advanced stages, with high blood tumor burden, it is preferable to start with debulking agents and then use ECP; in this scenario anti-CCR4 mogamulizumab can induce a high response rate, particularly in the blood, thus reducing the number of atypical cells." (PMID 35159143, 2022). "In xenograft murine models, CCR4 CAR-T therapy effectively eradicated cell leukemia and mice remained disease-free at the end of the study (however this was only 12 weeks duration), while the tumor continued growth in all mice treated with control T cells." (PMID 36059451, 2022). "Importantly, CCR4 and its ligands CCL17 and CCL22 produced by TLS mature DCs, macrophages or tumor cells were shown to be involved in the Treg recruitment to the inflamed sites." (PMID 36566320, 2022). "Treatments that decrease Treg infiltration or activity, such as a CCR4 antagonist, may be effective immunotherapeutics against multiple EBV+ tumor types." (PMID 35025968, 2022). "We should collect CCR4+CD8+ TILs and evaluate their response to tumor antigens." (PMID 36522365, 2022). "The CCL2-CCR2 signaling axis plays a role in the promotion of pathological angiogenesis in neoplastic disease, and the survival and invasion of tumor cells, without taking CCR4 into account." (PMID 36555280, 2022). "Additionally, CCR4 is the most studied receptor that can recruit Tregs into TME and promote tumor growth by binding to CCL22 or CCL17." (PMID 36246629, 2022). "This study determined that CCR4, TMCO1, and SPACA4 may be potential antigens for HNSCC mRNA tumor vaccine development, and patients with immune subtype C3 might benefit most from mRNA vaccination." (PMID 36671475, 2022). "CCR4-mediated chemotaxis is not sufficient to produce metastasis because it requires CCR4-positive Treg cells, which suppress the cytotoxicity of NK cells that eliminate tumor cells." (PMID 36555280, 2022). "All of this suggests that the chemokine receptor CCR4 is exclusively involved in the tumor-specific migration of Tregs without affecting its survival or suppressive activities." (PMID 35222362, 2022). "Anti-CCR4 mAb and anti-CCR8 mAb have been shown to selectively deplete tumor-infiltrating Tregs." (PMID 36225938, 2022). "CCL17 is a ligand for CCR4, which activates CCR4-expressing Th2 cells and regulatory T-cells (Tregs) and suppresses effector cells; KCNE4 may contribute to tumor cell survival through activation of Tregs via increasing CCL17 production." (PMID 35915077, 2022).